DES (desmin)
Diseases named in the same sentence as DES in open-access papers (continued):
Sharing a sentence is not in itself a finding about the gene and the disease.
tumor (continued). "Immunohistochemistry showed that the tumor cells positively expressed CD99 and vimentin, some cases could positively expressed NSE, but negatively expressed S100, neurofilament protein, desmin and keratin." (PMID 41267976, 2025). "Tumour cells showed cytoplasmic expression of vimentin and were negative to desmin, α-SMA, S-100 and c-Kit." (PMID 40045318, 2025). "The immunohistochemistry report revealed tumour cell expressing Desmin and negative for CD34 and CD117." (PMID 40955214, 2025). "Immunohistochemical analyses depicted that the tumor was positive for estrogen receptor, progesterone receptor, desmin, and α-smooth muscle actin, but negative for S100." (PMID 40527829, 2025). "Immunohistochemically, the tumor cells show variable expression of SMA and desmin." (PMID 40282503, 2025). "Immunohistochemically, the tumor cells show variable expression of SMA, desmin, and CD30." (PMID 40282503, 2025). "Although immunohistochemistry was conducted during the second examination, desmin and myogenin staining were negative, and tumor proliferative activity was not significantly elevated." (PMID 40703554, 2025). "Immunohistochemically, the tumor cells show positivity for SMA, h-caldesmon, and desmin." (PMID 40002892, 2025). "Immunohistochemically, the tumor cells tested positive for desmin, vimentin, SMA, and CD34 and negative for S-100 and CK." (PMID 38590660, 2024). "Immunohistochemically, these tumor cells show diffuse reactivity for cytokeratin and vimentin localized to the cytoplasmic inclusions, but not for desmin, smooth muscle actin, or other skeletal muscle markers." (PMID 39677213, 2024). "On immunohistochemical evaluation, tumor cells were positive for vimentin, smooth muscle actin, and desmin and negative for CD117, DOG1, and CD34." (PMID 39280874, 2024). "Tumor cell cytoplasm was positive for h-caldesmon, SMA, and desmin." (PMID 39497877, 2024). "The tumor presented as atypical spindle cells expressing vimentin and CD10, but without expression of epithelial markers (cytokeratin AE1/AE3, cytokeratin 8/18, desmin)." (PMID 39594178, 2024). "The tumor was positive for desmin, smooth muscle actin, and keratin; tumor staging, grade, and postsurgical follow-up were not completed as the patient expired postoperatively." (PMID 39544284, 2024). "Immunohistochemically, the tumor cells show variable expression of CD34, S-100 protein, and desmin." (PMID 39335118, 2024). "Tumor cell cytoplasm was positive for h-caldesmon, smooth muscle actin (SMA), and desmin." (PMID 39497877, 2024). "The tumor cells were negative for epithelial markers (cytokeratin), mesenchymal markers (desmin, smooth muscle actin), lymphoid markers (CD3 and CD20), and melanocytic markers (HMB45)." (PMID 39473659, 2024). "Immunohistochemical analysis revealed the following results: Tumor cells were negative for Ckp, positive for desmin and actin, negative for myogenin, positive for MyoD1, and negative for CgA, S-100, Syn, h-caldesmon, SMA, Sox-10, Pax-8, and GATA3." (PMID 39139286, 2024). "The tumor cells were immunohistochemically positive for vimentin, also they were positive for striated muscle markers, such as desmin & myogenin but negative for SMA." (PMID 39020398, 2024). "On immunohistochemical analysis, the tumor was positive for desmin, muscle actin, beta-catenin, and vimentin and negative for CD1 (c-kit), DOG1, S100, CD117, and Ki-67." (PMID 38846219, 2024). "In this case, the tumor cells were positive for keratin AE1/AE3, desmin, and smooth muscle actin." (PMID 39544284, 2024). "This tumor shows positive immunohistochemical reactions for smooth muscle actin and desmin, and a negative reaction for KIT (CD117)." (PMID 38512393, 2024).
tumor (continued). "On immunohistochemical evaluation, the tumor cells were diffusely positive for vimentin, smooth muscle actin, and desmin and negative for S100, CD117, and DOG1." (PMID 39280874, 2024). "Immunohistochemical (IHC) evaluation revealed tumor cell reactivity to Vimentin, Desmin, Myo D1, and Myogenin but was non-reactive for SMA and CK7." (PMID 36777814, 2023). "The tumor cells were positive for AE1/AE2, calretinin, WT-1, D2-40, HEG1, EMA, BAP1, and MTAP and negative for carcinoembryonic antigen, MOC-31, Ber-Ep4, ER, PgR, TTF-1, claudin 4, and desmin." (PMID 36896044, 2023). "Immunohistochemical examinations demonstrated positive staining of the tumor cells for cytokeratin, synaptophysin and chromogranin A, and negative for smooth muscle actin, desmin, S-100." (PMID 38152101, 2023). "IHC revealed that the tumor cells were positive for desmin, S100, and myogenin, and negative for CD34, SMA, P63, and CK." (PMID 37233406, 2023). "In some cases, low-grade myofibroblastic sarcoma can also have a histopathological resemblance to DF, and this can be confirmed with SMA, desmin, and nuclear ß-catenin positivity in this tumor, but not in DF." (PMID 37602060, 2023). "In addition, focal staining for Melan-A, weak chromogranin A staining, partial, patchy desmin staining and weak heterogonous NSE immunoreactivity was detected in the tumor cells." (PMID 35501497, 2023). "The tumor cells did not express pan-cytokeratin, desmin, MyoD1, Myogenin, Melan-A, HMB45, EMA, S-100, SOX-10, IgG4, and pan-TRK." (PMID 37735390, 2023). "Postoperative IHC revealed that the tumor was positive for desmin, S100, and EMA and negative for MyoD1, myogenin, CKpan, CD34, SMA, SOX-10, HMB, and MelanA." (PMID 37233406, 2023). "As the tumor was pan-cytokeratin and desmin negative, focally positive for caldesmon, and positive for smooth muscle actin, the diagnosis of pleomorphic leiomyosarcoma of the tongue was established." (PMID 36686144, 2022). "Unlike DAM, which is usually a desmin-positive tumour with retained nuclear expression of RB1, CAF is desmin-negative, with the loss of nuclear RB1 immunoreactivity." (PMID 35204448, 2022). "By immunohistochemistry, the tumor cells are positive for SMA and desmin." (PMID 35719719, 2022). "We found that Pan-TRK, S-100, and CD34 were positive by IHC analysis, while SOX10 and desmin were negative in the tumor." (PMID 35572973, 2022). "Immunohistochemical staining showed that the tumor cells were positive for vimentin and Bcl-2 but negative for S-100, desmin Syn, WT-1, EMA, CD34, and CD99; the Ki-67 index in tumor cells was 40%." (PMID 36482604, 2022). "The tumor cells characteristically co-express CD34 and desmin." (PMID 36086676, 2022). "Xenograft tumor of HCT 116 showed an increased expression of neuronal genes MAP2 and SYN1, neural stemness genes CDH2, MSI1, NCAM1, SOX2/9, VIM and ZEB2, and genes for mesodermal and endodermal tissues (ACP5, AFP, DESMIN, HNF4A and KRT8)." (PMID 33468253, 2021). "Immunohistochemically, the tumor cells were positive for smooth muscle actin, epithelial membrane antigen, desmin and certain cells for CD30 but negative for ALK-1, DOG-1, and for markers of lymphomas or other mesenchymal tumors of childhood." (PMID 37206935, 2021). "Tumor cells demonstrate positivity for CD34, Desmin and ASMA IHC stains." (PMID 33879215, 2021). "Tumor cells were nonreactive for SF-1, inhibin alpha, desmin, HHF35, HMB45, Melan A, MITF, c-kit, DOG1, cytokeratin AE1/AE3, h-caldesmon, STAT6, CD68, MDM2, CDK4, c17, DHEAST, 3BHSD, CD31, Factor 8, and ERG." (PMID 34797454, 2021). "In immunohistochemical analysis, tumor cells were positive for human melanoma black 45 (HMB45) and microphthalmia transcription factor (MITF), and some cells even for α‐smooth muscle actin (αSMA), caldesmon and desmin." (PMID 33119872, 2021).
tumor (continued). "In contrast, the tumor cells were nonreactive for SF-1, inhibin alpha, desmin, HHF35, HMB45, Melan A, MITF, c-kit, DOG1, cytokeratin AE1/AE3, h-caldesmon, STAT6, CD68, MDM2, CDK4, c17, DHEAST, 3BHSD, CD31, Factor 8, and ERG." (PMID 34797454, 2021). "Moreover, genes representing mesodermal or/and endodermal tissue differentiation (ACP5, ACTA2, BGLAP, CTSK, DESMIN, FOXA2) were activated in tumor." (PMID 33468253, 2021). "Immunohistochemically, the tumor cells are positive for SMA, desmin, and h-caldesmon." (PMID 32316685, 2020). "Immunohistochemically, the tumor cells show a distinct immunophenotype of polyphenotypic differentiation, including expression of epithelial (e.g., cytokeratin, EMA), muscular (e.g., desmin), and neural markers (e.g., NSE, Leu-7)." (PMID 32867125, 2020). "Unlike the distribution of macrophages, desmin-positive HSCs were only present in the non-tumor and peri-tumor regions of the liver, but not inside the tumor." (PMID 32382012, 2020). "Immunohistochemically, the tumor cells were positive for epithelial markers (AE1/AE3, EMA), a smooth muscle marker (desmin), and less specific sex-cord markers (CD56, WT-1, CD99), but negative for relatively specific sex-cord markers (α-inhibin, calretinin, FOXL2, and SF1)." (PMID 32921307, 2020). "Despite the resemblance of myoid cells, the tumor cells stain negative for desmin and positive for endothelial markers." (PMID 33194900, 2020). "Tumor cells were immunohistologically positive for α-smooth muscle actin and h-caldesmon; partially positive for desmin; negative for c-kit, CD34, DOG-1, and the S-100 protein; and showed a Ki-67 labeling index of 70–80%." (PMID 33006746, 2020). "In addition to cytoplasmic desmin/vimentin, few cells from 6 CAF primary cultures also expressed cytokeratin (6/15) presenting EMT of tumor cells." (PMID 32388727, 2020). "Immunohistochemically, tumour cells were intensely and diffusely positive for vimentin, as expected for a tumour of mesenchymal tissue origin, and variably positive for α-SMA and desmin." (PMID 32787426, 2020). "In this case, tumor cells were positive for desmin, αSMA, and h-caldesmon and negative for c-kit, S100, CD34, CAM5.2, EMA, CD163, and DOG1, supporting the diagnosis of PHL." (PMID 32648231, 2020). "Absence of staining for desmin is shown as an example indicating the tumor does not have striated muscle differentiation while positive control staining is shown in human skeletal muscle tissue." (PMID 32652895, 2020). "Immunohistochemical analysis showed that tumor cells tested positive for S-100 protein and negative for desmin." (PMID 32669088, 2020). "Immunophenotypically, the tumor was positive for vimentin, epithelial membrane antigen (EMA) and negative for CK-pan, CAM5.2, CD31, CD34, smooth muscle actin (SMA), desmin, anaplastic lymphoma kinase (ALK), calponin, TTF-1 and S-100 protein." (PMID 32039736, 2020). "The tumor cells were immunoreactive for vimentin, smooth muscle actin, and desmin and negative for S100." (PMID 32992611, 2020). "By well-controlled, routine immunohistochemical stains, the tumor cells were immunoreactive for vimentin, while they were negative for actin, desmin, S-100 and CD34 antibodies." (PMID 32605652, 2020). "Changes in the microvessel density of tumor plaques excised from the CAM were determined by desmin staining, as desmin is expressed by arterial as well as venous blood vessels of the CAM vascular network and is known to serve as a specific marker for CAM micovessels." (PMID 31583820, 2019). "The increase in desmin would suggest that it is not simply tumor shrinkage that leads to an increase of CD31-positive cells." (PMID 31852910, 2019). "However, recent immunochemistry studies have provided better evidences of the origin of this tumor which show positive for S-100 protein, neuron-specific enolase, and CD68 but negative for muscular markers such as myoglobin, keratin, and desmin." (PMID 27068886, 2018).
tumor (continued). "Immunohistochemical staining showed that the tumor cells were focally immunoreactive for S100 and were negative for desmin." (PMID 30364248, 2018). "The tumor cells showed positive immunostaining for SMA, desmin, ER, and PR." (PMID 28533481, 2017). "Histopathological examination revealed aggressive angiomyxoma with estrogen receptors positivity in 75% of the tumor cells, progesterone receptors in 80% of the tumor cells, actin and CD34 positivity in blood vessels, desmin positivity, and Ki67 positivity in 3% of the cells." (PMID 28944124, 2017). "Desmin, estrogen receptor (ER), and progesterone receptor (PR) were also found in the cells of the nodule, while tumor cells were negative for HMB-45 and S100." (PMID 28899426, 2017). "Immunohistochemical (IHC) staining of the patient’s tumour revealed only focal SMA positivity, whereas the tumour was negative for Desmin, Caldesmon, S100, CD34, EMA, Melan A, and Pan-CK." (PMID 28304377, 2017). "By immunohistochemistry, some tumor cells were weakly positive for epithelial membrane antigen (EMA), but they were negative for cytokeratin, smooth muscle actin (SMA), desmin, S-100, Melan-A, and CD34." (PMID 28471957, 2017). "On immunohistochemical examination, the tumor cells were negative for desmin, S100, smooth muscle actin, CD34, and CD117 and were positive for MUC4." (PMID 27247823, 2016). "Immunohistochemically, pan-keratin, thyroglobulin, and S100 were negative in tumor cells, whereas vimentin, desmin, and smooth muscle actin were found to be positive." (PMID 27080750, 2016). "In IHC, the tumor cells were negative for desmin, S-100, c-Kit, CK-AE1/AE3, EMA, CD31, CD117, CDK4, MDM2 and p63." (PMID 26337721, 2015). "Representative NT and PTC cells expressed some thyroid differentiation biomarkers and epithelial tumor marker as indicator of tumor purity, and were negative for desmin (mesenchymal marker)." (PMID 26636651, 2015). "Immunohistochemical staining showed that vimentin and SMA were positively expressed in these tumor cells, while desmin was only partially expressed; in contrast, no sign of S-100 or CD34 protein expression was found in these spindle-shaped tumor cells." (PMID 26303928, 2015). "In the present case, the tumour cells were strongly positive for CD34 and Bcl-2, but were negative for CD117, smooth muscle antigen, S-100, EMA and desmin expression, indicating that the tumour was an SFT." (PMID 25663869, 2015). "Immunohistochemically, the tumour cells were positive for vimentin, actin, desmin, and progesterone but negative for S100 protein, CEA, CKAE1/AE3, factor VIII." (PMID 25977826, 2015). "Immunohistochemical staining of the tumour revealed strong cytoplasmic positive staining for actin, desmin, and vimentin, but there was negative staining for keratin and S-100 protein." (PMID 26640482, 2015). "Immunohistochemistry was performed which revealed that the tumor cells were strongly positive for desmin and vimentin and negative for calretinin, inhibin, chromogranin, synaptophysin, S100, pan keratin, and CD68." (PMID 25685588, 2015). "Immunohistochemically, tumor cells from the lung were positive for SMA, CD163, F8, vimentin, and collagen IV, whereas they were negative for CD21, CD31, CD34, CD35, CD117, Bcl-2, CK7, CKlow, EMA, HMB45, desmin, myosin, s-100, and TTF-1." (PMID 25888833, 2015). "Immunohistological examination of the tumour showed that the tumour cells were weakly stained with desmin, but EMA staining was negative." (PMID 26640482, 2015). "SmoM2 tumors lacked cellular atypia and diffusely expressed desmin and actin in many tumor cells (more than 75% of all tumor cells)." (PMID 25759794, 2015). "Immunohistochemical staining of the tumour had shown positive staining for vimentin and weakly positive staining for actin as well as negative staining for desmin." (PMID 26640482, 2015).
tumor (continued). "Immunohistochemical staining showed strong expression of vimentin and smooth muscle actin (SMA) in the tumor cells, while desmin was only partially expressed; however, no sign of S-100 protein or CD34 expression was found in these cells." (PMID 26303928, 2015). "The pleomorphic tumor cells were strongly positive for desmin and focally positive for myoD1 but negative for myogen (Myf-4), CD117, CD34, and DOG1 IHC, suggesting rhabdomyosarcomatous differentiation." (PMID 25694839, 2015). "In contrast to the primary lesion, tumor cells of the recurrent lesion were negative for desmin and positive for CK." (PMID 25624890, 2015). "In our case, however, tumor cells showed focal positive staining for desmin and was not comfirmed the expression of desmin by RT-PCR analysis." (PMID 26208724, 2015). "The diagnosis of these rare tumours predominately depends on immunohistochemistry and the characteristic coexpression of melanocytic (HMB45 and/or melan A) and smooth muscle markers (actin and/or desmin)." (PMID 25821471, 2015). "Immunohistochemical staining revealed that the tumor cells were positive for AE1/AE3, cytokeratin (CK) 7, vimentin, cluster of differentiation (CD) 31 and E-cadherin, but showed no staining for CD10, CD34, factor VIII, CK20, carcinoembryonic antigen or desmin." (PMID 25120677, 2014). "Immunoreactivity for Vim, desmin and SMA was variable in the tumor cells." (PMID 24932260, 2014). "MSCs incorporation into tumor stroma is thus associated with a morphological shift toward CAF-like phenotype, including expression of myofibroblast-like cell markers (α-SMA, desmin, VEGF), proteins involved in the regulation of ECM structure (Tn-C, Tsp-1, SL-1) and tumor promoting factors." (PMID 25303976, 2014). "Immunohistochemistry showed that these tumor cells were positive for desmin, smooth muscle actin, estrogen receptor, and progesterone receptor and negative for S100, CD117, and CD34, confirming the smooth muscle origin of the tumor." (PMID 24991446, 2014). "It has been previously demonstrated using immunohistochemistry that the tumor cells usually express vimentin and smooth muscle actin, but are negative for desmin, and these results are in accordance with this proposal." (PMID 25120611, 2014). "Tumor cells were negative for muscle-specific actin, epithelial membrane antigen, smooth muscle actin, cytokeratin pan, S100, desmin, glial fibrillary acidic protein, myogenin, MyoD1 and F8." (PMID 24758544, 2014). "The tumor cells stained positively for vimentin, inhibin and α-smooth muscle actin, but not for the α-helical rod domain of desmin, which aided in confirming the diagnosis of ovarian leiomyoma." (PMID 25360170, 2014). "Immunohistochemical staining of the tumour showed positive reaction to the tumour cells for Vimentin, S100 protein, and Melan A and negative reaction for muscle actin, smooth muscle actin, desmin, and HMB-45." (PMID 25374957, 2014). "Similarly, positive staining for CD30 (Dako; Clone Ber-H2; 1:40 dilution), desmin (Dako; Clone D33; 1:100 dilution), and SMA (Dako; Clone 1A4; 1:100 dilution) was also observed in some tumor cells in the 2 cases." (PMID 24034896, 2013). "Immunoreactivity for vimentin and smooth muscle actin (SMA) was detected in the cytoplasm of the tumor cell, but not for desmin or cytokeratin." (PMID 23936706, 2013). "Nevertheless the number of cases stained by the neuroendocrine markers of Syn, CgA, S-100 and NSE, and myoepithelial markers of desmin was limited, no positive finding in all tumor cells was still a meaningful result." (PMID 23587094, 2013). "The tumor lacked reactivity for melanin-associated antigens HMB-45 and Melan-A, and for CD31, pan-cytokeratin (AE1/3) and desmin." (PMID 23628229, 2013). "In summary, the positive reactivity of CD34, Bcl-2, and SMA and negative reactivity of C-kit, S100, and desmin of the tumour were compatible with solitary fibrous tumour." (PMID 24490095, 2013).